EGFR (epidermal growth factor receptor)
Diseases named in the same sentence as EGFR in open-access papers (continued):
Sharing a sentence is not in itself a finding about the gene and the disease.
cancer (continued). "Given that previous work from our group, as well as from other groups, had shown that TIMP-1 can be predictive of outcome in CRC, and that TIMP-1 can promote cancer cell survival through the PI3K/AKT signaling axis, we reasoned that TIMP-1 could influence response to anti-EGFR therapy." (PMID 27509063, 2016). "In addition, MSI cases were characterized by accumulation of mutations in PIK3CA, ERBB3, HER2, and epidermal growth factor receptor (EGFR), but MSI cancers generally lacked targetable amplifications." (PMID 27233623, 2016). "We validate the gene activity score using data from the Cancer Cell Line Encyclopedia and drug sensitivity data for five compounds: BYL719 (PIK3CA inhibitor), PLX4720 (BRAF inhibitor), AZD6244 (MEK inhibitor), Erlotinib (EGFR inhibitor), and Nutlin-3 (MDM2 inhibitor)." (PMID 26864072, 2016). "Although sialylation in the TKI-resistant mutants suppresses EGFR tyrosine phosphorylation with the most significant effect on the Y1173 site, the sialylation effect was not strong enough to stop cancer progression by inhibiting the phosphorylation of these three sites." (PMID 27029067, 2016). "Further evaluation of signaling events post RT and EGFR inhibition for canine OSA cells are warranted, as such studies could shed more light on the potential mechanisms involved in this treatment and improve targeted therapeutic strategies for this cancer." (PMID 27245053, 2016). "Although varying frequency of activating somatic mutations across different populations is known in the literature for EGFR,22KRAS,23BRAF,24 and PIK3CA25, 26 in lung, colorectal, and other cancers, absence of PIK3CA mutations in Indian cases of RMS is surprising." (PMID 27562493, 2016). "Impairment of the EGFR/Ras/Raf/MEK/ERK cascade by anti-EGFR, anti-Raf, or anti-MEK anti-cancer drugs could enhance type I IFN response, giving rise to inflammatory events in the skin and possibly also in the intestinal tract, the two most important targets of their adverse events." (PMID 27322144, 2016). "miR-7 has been reported to suppress the key numbers of cancer cell signaling pathway, including EGFR/Ras/Raf/MEK/ERK1/2, EGFR/PI3K/Akt/mTOR, IGF1R/IRS, Integrin/FAK, Rac1/Pak1 and Ack1-mediated signaling transduction, which may implicated in tumorigenesis, progression and metastasis." (PMID 27764812, 2016). "In uninfected cells, EGFR transiently passes through Rab5 vesicles, but is not known to traffic to the Rab11-marked ERC except under exceptional conditions of cellular stress associated with drug treatment, cancer or immortalizaion." (PMID 27218650, 2016). "Small molecule inhibitors that target EGFR are undoubtedly successful, and the first-generation EGFR tyrosine kinase inhibitors (TKIs) such as gefitinib (IRRESA), elotinib (TARCEVA), lapatinib (TYKERB), and icotinib (CONMANA) have efficacy against several types of human cancers." (PMID 26848869, 2016). "In human cancer cell lines, EGFR signaling is not possible without AGR2’s presence." (PMID 27764193, 2016). "While the growth signal through phosphorylation of tyrosine residues on growth factor receptors such as EGFR appeared to be stopped by de-phosphorylation with a receptor-type tyrosine phosphatase, there has been no good explanation for the frequent overexpression of PTP-LAR in cancer cells." (PMID 27834817, 2016). "In addition, PAK4 lies downstream of EGFR in the ERBB signaling pathway; hence, the nine FDA-approved cancer drugs targeting EGFR should be assessed to see if they ameliorate the effects of PAK4 mutations and could be used to treat HGSOC patients." (PMID 27788148, 2016). "Therefore, the induction of apoptosis in cancer cells through targeting OPN and EGFR may be a helpful approach for the prevention and treatment of human HCC." (PMID 27888617, 2016).
cancer (continued). "We found blockade of EGF/EGFR axis reduced the expression of CCL2 in Cal27 cells, while suppression of CCL2/CCR2 axis decreased the expression of EGF in THP1 cells, suggesting that in HNSCC, the crosstalk between cancer cells and macrophages was also mediated by a positive feedback paracrine loop." (PMID 27888616, 2016). "It is intriguing that the inhibitory effects of EGFR tyrosine kinase inhibitor AG1478 on cell proliferation were more effective in β1-KO cells than in WT cells, which suggested that a treatment combining anti-EGFR therapy with anti-integrin drugs wound be important for cancer therapy." (PMID 26728650, 2016). "Moreover, actions of EGFR in regulation of cancer stemness markers including OCT4 and SOX2 were not consistent in EOC cells." (PMID 27708225, 2016). "EGFR is one of the most important biomarkers for cancer molecular classification, yet may be not an ideal therapeutic target in GBM." (PMID 26717039, 2016). "However, as is true for all currently approved targeted cancer therapies, suboptimal response and even complete resistance to EGFR-targeted therapy is not uncommon in patients whose tumors have aberrant EGFR signaling." (PMID 25871473, 2015). "We speculated that heterodimerization of ERβ1 and other isoforms activate non-genomic signaling pathways when cancer cells with both ERβ1 and other isoforms are treated with EGFR-TKI." (PMID 26096604, 2015). "The Epidermal Growth Factor Receptor (EGFR) family members EGFR, Human Epidermal growth factor Receptor-2 (HER2), and Human Epidermal growth factor Receptor-3 (HER3) are well established as proto-oncogenes that play key roles in the initiation and progression of human cancers." (PMID 25865227, 2015). "Consistent with our in vitro data, analysis of tissue microarrays and RNA sequencing expression data from The Cancer Genome Atlas (TCGA) revealed a wide distribution of DUSP4 expression in pan-negative samples and an inverse relationship between DUSP4 and EGFR expression." (PMID 26084293, 2015). "Finally, and in accordance with previous suggestions in different cancer types, we propose that the HGF/MET pathway might act as a primary resistance mechanism for EGFR inhibitors." (PMID 26319934, 2015). "Upon treatment with EGFR-inhibiting antibodies such as Cetuximab or Panitumumab, patients showed an overall survival benefit of 3–5 months when the cancer was wildtype for KRAS, but no benefit when the cancer was KRAS-mutated." (PMID 26299805, 2015). "Not all EGFR-expressing cancers respond to targeted inhibitor treatment." (PMID 26370727, 2015). "In order to define the molecular mechanism involved in contact-dependent fibroblast-induced cancer cell elongation, migration and invasion, we applied pharmacological inhibitors of several known invasion-promoting kinases (i.e. PI3K/AKT, c-MET, MAPK/ERK, EGFR or FGFR) to co-cultures." (PMID 25973543, 2015). "Using publicly available chromatin binding data sets we observed binding of several transcriptional regulators which lie downstream of EGFR, KRAS, PI3K and EMT signalling pathways, providing tangible leads for future functional studies aiming to decipher the regulators of MCT2 in cancer." (PMID 26035357, 2015). "The insulin/IGF system also contributes to CRC resistance to both conventional and targeted anti-cancer agents, leading to increased PI3K/Akt signaling that hinders the apoptotic signals triggered by chemotherapeutic drugs and desensitizes CRC cells to the effect of anti-EGFR antibodies." (PMID 26528439, 2015). "Furthermore, DTPs are detectable in many cancer celllines following treatment with multiple cytotoxic and targeted agents, whereasinduction of SOX2 appears to be strictly limited to targeted EGFR inhibition in cellsaddicted to mutant EGFR signaling." (PMID 25686219, 2015).
cancer (continued). "In addition to the role of ANO1 in cell-cycle progression and proliferation, ANO1 has recently been shown to be involved in oncogenic signaling by activating EGFR and CAMK pathways to promote cancer progression, and enhancing MAPK signaling for progression of cell cycle." (PMID 26305547, 2015). "Studies by Chung and other authors have proposed that the expression of EGFR may vary within cancer types due to the ratio of low to high affinity binding receptors, which are not differentiated between by the commonly used EGFR assays." (PMID 26149458, 2015). "In addition, some RTKs such as the epidermal growth factor receptor (EGF-R) have a pro-migratory potential; EGF-R is expressed in carcinoma cells of various origins and it stimulates actin-driven membrane protrusions in response to EGF during chemotactic cell migration." (PMID 25799492, 2015). "However, the association between the EGFR signaling pathway and PDE4D has not been reported in cancer cells." (PMID 25289091, 2014). "Therefore, induction of autophagy leading to increased EGFR degradation, when combined with EGFR-TKIs, could be one of the promising therapeutic options for EGFR TKI-resistant cancer cells with EGFR dependency." (PMID 25486409, 2014). "Nonetheless, the contributions of negative EGFR regulators are still underestimated, although understanding of their activities might form the foundation for a more effective anti-cancer approach." (PMID 25301722, 2014). "While reduction of PGE2 by erlotinib has been reported, we could not detect PGE2 reduction by EGFR inhibition suggesting that the fluctuation of PGE2 production by EGFR blockade is affected by cancer heterogeneity." (PMID 25240937, 2014). "One mechanism that has been proposed is that EGFR regulates the Notch pathway through the repression of the global transcriptional co-repressor, Goucho/TLE (Transducer like Enhancer of split) to attenuate Notch-mediated gene activation and promote growth of cancer cells." (PMID 25566499, 2014). "Epidermal growth factor receptor (EGFR) family of tyrosine kinase (TK) play a vital role in cancer proliferation and it is suggested that any agent would inhibit the TK activity and may have a considerable role in cancer treatment." (PMID 25177693, 2014). "Alcohol promotes cancer progression by inducing gene expression of epithelial-mesenchymal transition (EMT) genes, such as the transcription factor Snail, by increasing epidermal growth factor receptor (EGFR) transactivation and activating matrix metalloproteinases (MMPs)." (PMID 24886599, 2014). "Recent studies suggest that combining EGFR kinase inhibitors and anti-EGFR antibodies may be more effective than either alone, perhaps because EGFR is able to maintain cancer cell survival independent of its kinase activity." (PMID 25594061, 2014). "Cancer cells harboring T790M represent not only resistance to EGFR-TKI but also clones proliferating relatively slowly, which suggested that de novo T790M predicted poor prognosis after EGFR-TKI and acquired T790M conferred superior prognosis after a long period of enrichment of T790M mutant clones." (PMID 25405807, 2014). "Again, given that EMT processes induce downregulation of epithelial markers and that EMT facilitates intravasation of cancer cells within the bloodstream, the presence of EGFR-negative CTCs could identify cancer cells with more proclivity to metastasize." (PMID 25105871, 2014). "Determine variability of epidermal growth factor receptor (EGFR)-pathway proteins and their phosphorylation status with respect to tissue processing as examples of critical clinical biomarkers whose expression and activity level inform targeted therapy evaluation in cancer." (PMID 25526028, 2014). "Recent preclinical studies suggest that combining EGFR kinase inhibitors and anti-EGFR antibodies may be more effective than either alone, perhaps because EGFR is able to maintain cancer cell survival independent of its kinase activity." (PMID 23435217, 2013).
cancer (continued). "This assay could also be useful for routine monitoring of circulating EGFR in cancer patients who are not taking cetuximab or panitumumab." (PMID 23990977, 2013). "EGFR and HER2 overexpression is observed in numerous types of cancer, nevertheless, the susceptibility of patients with non-small cell lung cancer (NSCLC) to therapy with EGFR and HER2 tyrosine kinase inhibitors (TKIs) depends on mutations present in the respective coding genes (driver mutations)." (PMID 24137465, 2013). "For example, the epidermal growth factor receptor (EGFR) is a cytoplasmic transmembrane receptor of tyrosine kinase family involved in the regulation of the proliferation, motility, and differentiation in a variety of cell types, and is highly expressed in cancer." (PMID 23936765, 2013). "Furthermore, EGFR blocking, using an αEGFR antibody that neutralizes EGFR by competition with EGF on the external domain of EGFR, also resulted in increases in IL-6 production from cancer cells." (PMID 23592411, 2013). "However, given that the specific locus in the EGFR with positive selection was located in a non-functional intron, the real function of this intron in the evolution of cancers requires further attention." (PMID 24223781, 2013). "The upregulation of epidermal growth factor receptor (EGFR) and vascular endothelial growth factor (VEGF), dysregulated microRNA (miRNA), and activation of cancer stem cell (CSC)/epithelial-mesenchymal transition (EMT) programs are involved in oncogenesis and progression of both cancer types." (PMID 23819113, 2013). "Usually, EGFR mutations are characteristic of tumors in the non-smoker groups of patients, particularly among Asian women, while KRAS mutations are often detected in smoking-associated cancer types." (PMID 23817662, 2013). "In addition to downregulating EGFR, miR-7 targets several other genes involved in EGFR signaling and tumorigenesis, indicating that miR-7 negatively regulates EGFR signaling in several types of cancers." (PMID 24349829, 2013). "Since the distribution of EGFR in solid tumors is heterogeneous, we organized the carcinoma A431 cells in a focal configuration surrounded by non-transformed, rat small intestine epithelial IEC6 cells, as evident from the borderline between the A431 and IEC6 cells." (PMID 23857061, 2013). "In addition, among the several ligands of EGFR, transforming growth factor-α (TGF-α), a potent ligand for EGFR, is reported to be involved in regulation of MUC5AC expression in human pulmonary mucoepidermoid carcinoma cells." (PMID 24027752, 2013). "Another report showed that lapatinib, a dual TKI of EGFR and HER2, inhibits the nuclear transport of EGFR and HER2 and sensitizes cancer cells to fluoropyrimidine by downregulating thymidylate synthase, which is frequently overexpressed in fluoropyrimidine-resistant cancer cells." (PMID 22520625, 2012). "Combining the current EGFR assay in a multiplex fashion with similar assays for IGF-1R and cMet could provide for optimal therapeutic choice and a drug resistance biomarker panel to drive targeted therapeutic efforts in NSCLC, as well as other cancers." (PMID 22554165, 2012). "For example, targeting of Epidermal Growth Factor Receptor (EGFR) with small molecules or monoclonal antibodies has been reported to offer no survival benefit, despite the fact that EGFR is the most common genomically altered oncogene in GBM, and targeting EGFR has shown benefit in other cancers." (PMID 23056179, 2012). "In one recent study, it was found that the use of antibodies against SP induces cell death in several cancer cell types and that this effect is accompanied by a decrease in signaling through the MAPK pathway and a decrease in the basal activity and expression of Her2 and EGFR." (PMID 22545017, 2012).
cancer (continued). "For example, sole use of ERK or AKT inhibitor may not bring a good therapeutic effect even to patients with EGFR-addicted cancers." (PMID 22194952, 2011). "Furthermore, a significant proportion of cancer patients show no benefit from anti-EGFR therapies because of the independent activation of downstream signalling, especially the Ras/Raf/MAPK pathway." (PMID 21943394, 2011). "In accordance with the low prevalence of genetic amplification of the EGFR gene in this type of cancer, none of the 38 patients exhibited increased EGFR gene copy number in a recent phase II trial of cetuximab in combination with mFOLFOX6 in gastric and OGJ cancer." (PMID 22152101, 2011). "Binding of Trastuzumab (Herceptin®) or Cetuximab (Erbitux®) to Lm-spa+, two clinically approved monoclonal antibodies directed against HER2/neu and EGFR/HER1, respectively, triggers InlAB-independent internalization into non-phagocytic cancer cell lines overexpressing the respective receptors." (PMID 21745384, 2011). "Interestingly, in cancer tissues the expression level of EGFR is correlated with prognosis, but not with responsiveness to EGFR inhibitor treatment." (PMID 22035226, 2011). "Cancer cells without amplification of the EGFR gene showed low copy number values (<0.7)." (PMID 22140428, 2011). "Since the EGFR is not constitutively active in normal tissue, the mAb806 is cancer-specific." (PMID 24212795, 2011). "Some growth factors, including epidermal growth factor receptor (EGFR) and vascular endothelial growth factor receptor (VEGFR), and various signal transduction pathways that play important roles in the progression, proliferation and metastasis of various cancers have been identified." (PMID 24212807, 2011). "Additionally, stimulation of the EGFR by a GRK/β-arrestin pathway is not identical to activating EGFR directly, and there is a report indicating that carvedilol inhibits multiple cancer cell lines growth in vitro." (PMID 21476970, 2011). "Wnt ligands can activate EGFR signaling through their 7-transmembrane domain receptor Frizzled while EGFR can activate β-catenin via receptor tyrosine kinase-PI3K/Akt pathway; EGFR has been shown to form a complex with β-catenin and increase the invasion and metastasis of cancer cells." (PMID 20828404, 2010). "Indeed, the EGFR tyrosine kinase inhibitors such as lapatinib and gefitinib, and the HER2/neu-targeted agent trastuzumab, have been shown to possess notable antitumor activity in several types of cancers." (PMID 20300520, 2010). "Some studies have reported positive regulation of Epidermal Growth Factor Receptor (EGFR) downstream signalling through ERK and PI3-K/AKT following calcium-mediated formation of E-cadherin intercellular contacts in monocultures of normal keratinocytes and cancer cell lines, respectively." (PMID 21049033, 2010). "Whether EGFR amplification as determined by FISH is a reliable indicator of EGFR inhibitor sensitivity for other types of cancers has not yet been conclusively assessed." (PMID 20037743, 2010). "Thus, MKP-1 overexpression is a potential negative biomarker of response to certain anti-cancer agents including anti-EGFR therapy." (PMID 20234366, 2010). "Given the role of EMT in multiple aspects of cancer progression, targeting EMT could contribute both to increased sensitivity to standard chemotherapy while also improving response towards growth factor directed therapies, such as those against EGFR signaling." (PMID 24281219, 2010). "We showed that inhibition of HIF-1α is required, although it may not be sufficient, to mediate the response of cancer cells to EGFR-targeted therapy." (PMID 21209911, 2010). "Of further interest, the link between EGFR mediated signaling and activation of TWIST1 in other cancers supports the intriguing possibility that this pro-invasive signaling network may activate specific micro-environmental changes in invasive GBM that correlate with specific MR imaging features." (PMID 20847921, 2010).